BAG3 (BAG cochaperone 3)
Diseases named in the same sentence as BAG3 in open-access papers (continued):
Sharing a sentence is not in itself a finding about the gene and the disease.
idiopathic cardiomyopathies (1 paper, 2024). "Among the 24 hallmark gene sets enriched in both idiopathic cardiomyopathies and ischemic disease, 15 gene sets had at least 3 proteins with BAG3-interaction." (PMID 39457090, 2024). "Proteins with BAG3-interaction were identified in all the 28 hallmark gene sets enriched in idiopathic cardiomyopathies and/or ischemic disease." (PMID 39457090, 2024).
idiopathic pulmonary fibrosis (1 paper, 2022). Idiopathic pulmonary fibrosis (IPF) is a nonneoplastic pulmonary disease that is characterized by the formation of scar tissue within the lungs in the absence of any known cause. "Given the role of the BAG3‐mediated autophagy under pathological conditions, it was interesting to study this autophagic pathway in idiopathic pulmonary fibrosis (IPF)." (PMID 35834635, 2022).
insulinoma (1 paper, 2015). "We then chose to use an established mouse insulinoma cell line, β-TC-6, to further investigate the role played by BAG3 in endocrine pancreatic cells." (PMID 25766323, 2015). "Indeed silencing BAG3 in β-TC-6 mouse insulinoma cells results in reduced intracellular content of insulin and in its increased secretion in response to glucose stimulation." (PMID 25766323, 2015). "Indeed using a mouse insulinoma β-TC-6 cell model here we show that BAG3 silencing affects F-actin polymerization state resulting in increased insulin secretion." (PMID 25766323, 2015).
ischemic cardiomyopathies (1 paper, 2024). "Among the 24 hallmark gene sets enriched in both idiopathic and ischemic cardiomyopathies, 15 gene sets had at least 3 proteins with BAG3 interaction." (PMID 39457090, 2024). "BAG3-interaction were identified in each of the 28 hallmark gene sets enriched in the idiopathic and/or ischemic cardiomyopathies." (PMID 39457090, 2024).
ischemic stroke (1 paper, 2025). A stroke disorder caused by obstruction of blood flow to the brain, due to thrombotic (local blood clot formation) or embolic (due to a blood clot or other material traveling from another site) event. "Previous research reported that the overexpression of BAG3 alleviated damage induced by ischemic stroke by activating autophagy and inhibiting apoptosis." (PMID 40711315, 2025).
large cell carcinoma (1 paper, 2014). A malignant epithelial neoplasm composed of large, atypical cells. "Normal lung tissue did not express BAG3 while we detected the expression of BAG3 by immunohistochemistry in all the 13 squamous cell carcinomas, 13 adenocarcinomas and 4 large cell carcinomas." (PMID 25149536, 2014).
lentivirus infection (1 paper, 2019). Virus diseases caused by the Lentivirus genus. "Furthermore, ectopic expression of BAG3 through lentivirus infection could activate PSCs, evidenced by elevated α‐SMA expression." (PMID 31119886, 2019).
long QT syndrome (1 paper, 2015).
lupus erythematosus (1 paper, 2023). An autoimmune, connective tissue chronic inflammatory disorder affecting the skin, joints, kidneys, lungs, heart, and the peripheral blood cells. "BAG3 directly interacts with HSP7C, which is targeted by forigerimod acetate, a phase 3 compound for lupus erythematosus." (PMID 37126556, 2023).
memory impairment (1 paper, 2024). "Our results suggest that TBI results in a reduction of BAG3 and ALP inefficiencies, which lead to ptau accumulation and memory impairments in mouse models and post-mortem human brain tissue." (PMID 39394356, 2024).
muscular disease (1 paper, 2017). Myopathy is a peripheral nervous system disease consisting of any abnormal condition or disease of the muscular tissues; commonly designates a disorder involving skeletal muscle. "Conversely, mutations in small HSPs such as HSPB1, HSPB3, HSPB5, HSPB8 and the co-chaperones DNAJB6 and BAG3 have all been associated with motor neuron and muscular diseases." (PMID 28396624, 2017).
myasthenia gravis (1 paper, 2025). Myasthenia gravis (MG) is a rare, clinically heterogeneous, autoimmune disorder of the neuromuscular junction characterized by fatigable weakness of voluntary muscles. "CA3 was found to be a binding partner of Bcl2-Associated Athanogene 3 (BAG3) in myasthenia gravis—a chronic autoimmune neuromuscular disorder characterized by weakness in skeletal muscles." (PMID 41465490, 2025). "CA3 has previously been implicated in autophagy-mediated protein degradation, offering protection against the neuromuscular disorder, myasthenia gravis, through its interaction with BAG3." (PMID 41465490, 2025).
myotilinopathy (1 paper, 2016). "The CASA complex comprises the chaperones HSPB8/Hsp22 and HSPA8/Hsc70, and the co-chaperone BAG3 that were also over-represented in myotilinopathy aggregates." (PMID 26842778, 2016).
promyelocytic leukemia (1 paper, 2014). "In addition, a previous research also supported the antiproliferative function of BAG3 in human promyelocytic leukemia HL-60 cells." (PMID 24895585, 2014).
prostate tumor (1 paper, 2023). "Compared to the normal tissue, the levels of CENPA, ADCK5, FOXM1, TFAP4, and MAPK were up-regulated in prostate tumor tissue, with a decrease in the expression of LGALS3 and BAG3." (PMID 36891298, 2023).
sarcoid (1 paper, 2013). "We demonstrate that BAG3 is selectively expressed in sarcoid tumour samples and highlight its pro-survival role in EqS04b, a sarcoid-derived cell line harbouring BPV-1 genome." (PMID 23876161, 2013).
SARS-CoV infection (1 paper, 2015). "Finally, quantitative proteomics analysis revealed that SARS-CoV infection significantly upregulates BCL2-associated athanogene 3 (BAG3), a protein linked to regulation of the autophagy pathway." (PMID 26287230, 2015).
seminoma (1 paper, 2023). A radiosensitive malignant germ cell tumor found in the testis (especially undescended), and extragonadal sites (anterior mediastinum and pineal gland). "BAG3 is notably elevated in seminoma compared to both non-seminoma and normal testicular tissue." (PMID 37834333, 2023).
Stroke (1 paper, 2025). Sudden impairment of blood flow to a part of the brain due to occlusion or rupture of an artery to the brain. "Our study demonstrated that MSTRG.151823.1 modulates the expression of multiple apoptosis-related genes, including Bag3, Serpine1, and Il6r, following stroke." (PMID 39847586, 2025).
type 1 diabetes (1 paper, 2020). "Our data evidenced that STZ-induced type 1 diabetes increased oxidative stress, depressed BAG3, Bcl-2, CaSR and p-eNOS expression and evoked vascular dysfunction in vasoconstriction and vasodilation of the mesenteric arterioles." (PMID 32751309, 2020).
urinary bladder tumours (1 paper, 2013). "This hypothesis was also supported by other studies on BPV-induced bovine urinary bladder tumours in which high levels of E5 were found to correlate with BAG3 overexpression (F. Roperto, personal communication)." (PMID 23876161, 2013).
cancer (98 papers, 2009 to 2026). A tumor composed of atypical neoplastic, often pleomorphic cells that invade other tissues. "CREB3L4 is an endoplasmic reticulum membrane-bound transcription factor that has been shown to regulate the expression of Bcl-2 associated athanogene 3 (BAG3), a co-chaperone protein involved in autophagy and survival signaling in various cancers." (PMID 42098970, 2026). "The BAG3 (Bcl-2-associated athanogene 3) protein is a multifunctional co-chaperone of Hsp70 protein with an important involvement in tumor biology, particularly in cancer cell survival, resistance to therapy, and tumor development." (PMID 40507324, 2025). "BAG3 has been implicated in various human diseases, including cancer, myopathies, and nervous system diseases." (PMID 38297320, 2024). "BCL-2-associated athanogene 3 (BAG3) is an anti-apoptotic protein that plays an essential role in the onset and progression of multiple cancer types." (PMID 38297320, 2024). "Bcl2-associated athanogene 3 (BAG3) is expressed by multiple cancer types, including PDAC, and correlates with poor prognosis." (PMID 32116785, 2020). "In cancers, high expression of BAG3 has been linked to resistance to chemotherapy and knockdown with increased sensitivity." (PMID 32093037, 2020). "Noteworthy, dysfunction and deregulation of BAG3 and its pathway are pathophysiologically linked to myopathies, cancer, and neurodegenerative disorders." (PMID 33158300, 2020). "Bcl-2 associated athanogene 3 (BAG3) is an important molecule that maintains oncogenic features of cancer cells via diverse mechanisms." (PMID 30910998, 2019). "Bcl2-associated athanogene 3 (BAG3) is a 575 amino acid anti-apoptotic protein that is constitutively expressed in the heart, skeletal muscle, and some types of cancers." (PMID 30792263, 2019). "BAG3 is constitutively expressed in multiple types of cancer cells and its high expression is associated with tumour progression and poor prognosis of PDAC." (PMID 31119886, 2019). "Many studies have reported a high level of BAG3 expression in cancer cells, and this has been associated with poor prognosis in patients with PDACs." (PMID 31001483, 2019). "In this manuscript, we investigate a role for the BCL2- Associated Athanogene 3 (BAG3) gene in driving cancer cell proliferation by regulating signalling pathways in TNBC." (PMID 29644001, 2018). "XIAP is a direct inhibitor of caspase activity, while increased expression of BAG3 in cancers is linked to the maintenance of cell survival, treatment resistance, and increased metastasis." (PMID 26799209, 2016). "BAG3 (Bcl2-associated athanogene-3), a multifunctional protein found in many tissues, is particularly abundant in cardiac and skeletal muscle tissues, as well as a variety of cancers." (PMID 39198407, 2024). "Another ATAC-seq peak predicted to regulate BAG3 transcription was found to be significantly associated with cellular resistance to 5-FU and paclitaxel treatment, in line with the results that BAG3 renders cancer cells unresponsive to 5-FU and paclitaxel." (PMID 36077628, 2022). "Aberrant expression of BAG3 has been linked to different cancer entities." (PMID 35488119, 2022). "Bcl2-associated athanogene 3 (BAG3) is a 575 amino acid anti-apoptotic protein that is constitutively expressed in the heart, skeletal muscle and some cancers and serves as a co-chaperone of both the constitutively and non-constitutively expressed heat-shock proteins (Hsc/Hsp)." (PMID 25925243, 2015). "Indeed, reduced motility of BAG3-deficient mouse endothelial fibroblasts and BAG3 depleted cancer cell lines was observed." (PMID 24362507, 2013). "This elevation in BAG3 may arise due to cellular stress and growth factors found in cancerous cells and has been associated with chemoresistance and adverse outcomes in numerous cancer types." (PMID 36980278, 2023). "This HSP70-BAG3 complex recruits LC3 to ubiquitinated substrates, positioning BAG3 as a critical regulator of mitophagic clearance in cancer cells." (PMID 40873580, 2025).
cancer (continued). "Specifically, analysis using the GEPIA database revealed that BAG3 mRNA expression is higher in tumors compared to normal tissues across multiple cancers, including HNSCC, and that elevated BAG3 levels are associated with poorer clinical outcomes." (PMID 40507324, 2025). "BAG3 is constitutively expressed in the heart, but it is also found in the skeletal muscle, brain, peripheral nervous system, and various forms of cancer." (PMID 40278180, 2025). "Based on this assumption, we analyzed the expression and secretion of BAG3 in 24 cancer cell lines representing ten types of cancer and compared these results with samples from primary tumors." (PMID 41367874, 2025). "Multivariable logistic regression was used to evaluate the association of common variants in TTN and BAG3 with late-onset CCM risk, adjusting for relevant demographic and cancer treatment exposures." (PMID 40540274, 2025). "Using Tumor IMmune Estimation Resource (TIMER), The Cancer Genome Atlas (TCGA), and Gene Expression Omnibus (GEO) database, we explored the expression, prognostic value, and clinical correlations of BAG3 in KIRC." (PMID 38297320, 2024). "In cancer specifically, BAG3 has been demonstrated to enhance the growth and migration of a range of tumor cells." (PMID 39030175, 2024). "Despite the progressive unravelling of BAG3’s biological role and its increasing attractiveness as a therapeutic target in cancer, very few modulators have been identified so far." (PMID 39519692, 2024). "This complicated interplay emphasizes the multifaceted nature of BAG3’s role in tumor formation and its potential as a therapeutic target in the ongoing battle against cancer." (PMID 39198407, 2024). "Within the complex environment of cancer biology, BAG3 emerges as a key player, regulating a wide range of cellular events required for tumor growth and survival." (PMID 39198407, 2024). "The expression levels of BAG3 in various human cancers were evaluated according to the TIMER database." (PMID 38297320, 2024). "In intermediate-grade cancer, BAG3 had a positive correlation (r = 0.604) with Inverse Difference T2WI, and TRAIL.R2 showed a positive correlation (r = 0.659) with Contrast T2WI." (PMID 38791417, 2024). "Given the pleiotropic functions of BAG3 in various cancer hallmarks, we now aimed to further analyze the molecular processes underlying BAG3‐driven malignancy in GBM, including domain‐specific functions of BAG3 in promoting tumor aggressiveness." (PMID 38655699, 2024). "There is increasing evidence that the co‐chaperone BAG3 serves as a central hub molecule in cancer cell signaling, involving a diverse set of oncogenic mechanisms on the cellular level as well as in the tumor microenvironment." (PMID 38655699, 2024). "To further verify the protein expression level of BAG3 in KIRC, we used IHC to detect BAG3 protein expression in 78 cancer samples and 54 para-cancer samples." (PMID 38297320, 2024). "Gene Set Cancer Analysis (GSCA) was utilized to scrutinize the prognostic value of BAG3 methylation." (PMID 38297320, 2024). "In summary, BAG3 has a potent oncogenic function and acts as a central hub protein promoting multiple cancer hallmarks, which makes it a very interesting therapeutic target." (PMID 38655699, 2024). "Taken together, these studies strongly support a role for BAG3 in cancer biology although many of the mechanisms responsible for its effects remain to be clarified." (PMID 36980278, 2023). "Li and colleagues concluded that JG-98, an allosteric inhibitor of the BAG3-Hsp70 interactome, had antiproliferative activity on cancer cell lines from various origins." (PMID 36980278, 2023). "Another role for BAG3 in cancer is its involvement in angiogenesis as neo-angiogenesis is critical for the growth and progression of cancer cells." (PMID 36980278, 2023).
cancer (continued). "BAG3 is an essential regulator of cell survival and has been investigated in the context of heart disease and cancer." (PMID 37576499, 2023). "It has also been shown that BAG3 can induce vascular endothelial growth factor (VEGF) in cancer cells, thus supporting angiogenesis, and knockdown of BAG3 resulted in reduced VEGF." (PMID 36980278, 2023). "Multiple previous studies have demonstrated that BAG3 interacts with Hsp70 to increase the expression of certain anti-apoptotic proteins and thus influence cancer cell survival and growth." (PMID 37576499, 2023). "The fundamental role of BAG3 in the biology of cancer cells is identical but physiologically opposite to that in the heart." (PMID 36980278, 2023). "It is not surprising that BAG3 is a target of cancer cells because BAG3 plays a critical role in protecting the heart from damage in response to heat and other signals that are expressed by cancer cells." (PMID 36980278, 2023). "In these processes, a co-chaperone Bag3 links Hsp70 with signaling pathways that control cancer development." (PMID 36077705, 2022). "Specifically, we found compound 6 as a new BAG3 modulator with a relevant antiproliferative effect on two different cancer cell lines (IC50: A375 = 19.36 μM; HeLa = 18.67 μM)." (PMID 35163936, 2022). "Due to its involvement in malignant transformation, BAG3 has emerged as a potential and effective biological target to control multiple cancer-related signaling pathways." (PMID 35163936, 2022). "It is worth noting that in the same paper, the authors reported that BAG3 knockdown in cancer cells favors the recruitment of Argonaute 2 (Ago2) to IL‐6 mRNA, which results in the IL‐6 mRNA destabilization and finally in the reduction of fibrosis onset." (PMID 34741483, 2022). "As the regulatory molecule of autophagy, BAG3 plays a vital role in maintaining cell homeostasis, which has attracted extensive attention in recent years, especially in cancer biology." (PMID 36228497, 2022). "Several studies addressed the role of BAG3 in sustaining growth and survival of cancer cell and also shed light on the different mechanisms in which the intracellular protein is involved." (PMID 34741483, 2022). "These analyses are consistent with the indispensable role of BAG3 in cancer progression and tumor resistance to therapy." (PMID 36727051, 2022). "Recently, we uncovered that Bag3 directly interacts with another transcription factor, a major regulator of cell polarity and cancer development—Yap." (PMID 36077705, 2022). "In its function in cancer signaling, Hsp70 collaborates with a co-chaperone Bag3, which is co-elevated with Hsp70 in many tumor types." (PMID 36077705, 2022). "Several pieces of evidence have been reported a pro‐tumor effect of BAG3 in several cancers, while its silencing has a detrimental impact both in tumoral cell growth and metastatic potential." (PMID 34741483, 2022). "Recent studies proved that BAG3 can effectively induce 5-fluorouracil and paclitaxel resistance in cancer cells." (PMID 35449156, 2022). "Since there is a broad involvement for BAG3 in multiple different cancer types, research has focused on BAG3 inhibitors." (PMID 34831344, 2021). "One confounding factor in developing anti-BAG3 therapeutics for cancer is that BAG3 plays an essential role in proper heart function." (PMID 34831344, 2021). "In cancer, BAG3 has been reported to be responsible for modulating processes such as cell survival, cell adhesion, metastasis and angiogenesis." (PMID 33158300, 2020). "In malignant diseases, BAG3 mostly exerts oncogenic functions and is known to regulate several key hallmarks of cancer, including cell survival, cell adhesion, metastasis, and angiogenesis." (PMID 32121220, 2020). "BAG3 is highly conserved and is expressed in all mammalian tissues, with highest expression in cardiac and skeletal muscle, but also in many cancer tissues." (PMID 32093037, 2020).